CTSS (cathepsin S)
Diseases named in the same sentence as CTSS in open-access papers (continued):
Sharing a sentence is not in itself a finding about the gene and the disease.
pulmonary diseases (11 papers, 2013 to 2026). "Herein, we review the significance of CTSS signaling in pulmonary diseases and associated comorbidities." (PMID 32398133, 2020). "Dysregulated CTSS expression or activity has been linked to several non-pulmonary diseases or outcomes of disease that are frequently observed as pulmonary comorbidities or additional symptoms such as cardiovascular disease and metabolic complications." (PMID 32398133, 2020). "Among the proteases associated with lung diseases, CTSS is unique in the sense that it has activity at neutral pH, i.e. it could be active within the lung and may contribute to disease initiation." (PMID 32398133, 2020). "A gene microarray analysis unveiled Cathepsin-S (with an AUC of 0.80) in alveolar macrophages as a potential differentiator between sarcoidosis and other lung diseases." (PMID 38250062, 2023). "Here we provide a brief overview of several pieces of data which suggest that CTSS may play a major role in extra-pulmonary disease progression and provide evidence that targeting CTSS may also be a plausible means to treat comorbidities associated with pulmonary diseases." (PMID 32398133, 2020). "A number of studies suggest that CTSS has potential as a prognostic biomarker, for example, as a surrogate marker of lung disease progression." (PMID 32398133, 2020). "Targeting CTSS represents a potential therapeutic for several pulmonary diseases and their comorbidities." (PMID 32398133, 2020). "Targeting CTSS represents a potential therapeutic treatment for several pulmonary diseases and their comorbidities." (PMID 32398133, 2020). "CTSS is particularly relevant in the context of pulmonary disease due to its ability to exert elastase activity, inactivate airway host defense proteins, induce ECM remodeling and alter mucus production across a wide pH range." (PMID 32398133, 2020). "Research suggest that modulation of CTSS could be beneficial in a range of pulmonary diseases as well as extra-pulmonary comorbidities." (PMID 32398133, 2020). "Therefore, CTSS appears to play a role in autoimmune responses and represents a potential therapeutic target to treat these diseases in addition to the pulmonary diseases already outlined in this review." (PMID 32398133, 2020). "Therefore, mounting data suggests that CTSS is a significant player in pulmonary and non-pulmonary disease progression that may impact on patient mortality." (PMID 32398133, 2020). "In this review, we will focus on one cysteine protease in particular, cathepsin S (CTSS), and outline the research supporting its growing importance in pulmonary diseases and the potential of targeting of CTSS as a therapeutic option." (PMID 32398133, 2020). "Given the remit of this review, it would be expected to address clinical trials undertaken to examine the efficacy of CTSS inhibitors in pulmonary disease, however, no such trials have been carried out despite promising preclinical data." (PMID 32398133, 2020). "Indeed, CTSS has been proposed as a biomarker and therapeutic target in diverse pulmonary diseases, and preclinical studies in cystic fibrosis and COPD models show that CTSS inhibition alleviates mucus hypersecretion, inflammation, and functional decline (46, –, 48)." (PMID 41258714, 2026).
Arthritis (10 papers, 2005 to 2021). Inflammation of a joint. "Consistently, a collagen-induced arthritis mouse model showed that disease progression was diminished in Cathepsin S-deficient animals." (PMID 33946524, 2021). "Moreover, it was demonstrated that impairment of Ii degradation and diminished collagen-induced arthritis were observed in cathepsin S-deficient mice." (PMID 20877570, 2010). "In mice, knockout of cathepsin S prevents collagen-induced arthritis, whereas increased circulating cathepsin S protein levels have also been detected in RA patients." (PMID 31493964, 2020).
chronic kidney disease (10 papers, 2014 to 2025). Impairment of the renal function secondary to chronic kidney damage persisting for three or more months. "CTSS is also a biomarker of chronic kidney disease, and as the glomerular filtration rate decreases, CTSS increases, exacerbating inflammation-associated endothelial dysfunction." (PMID 38764052, 2024). "In a mixed chronic renal disease/apo E deficiency mouse model, a high cholesterol diet produced high-level cathepsin S protein expression and increased degradation of elastin fibers." (PMID 35453881, 2022). "In adults with chronic kidney diseases, increased serum levels of cathepsin S and MMP-2 are associated with aortic stiffening." (PMID 24743169, 2014). "Recent research efforts have elucidated the key role of CTSS in influencing the pathogenesis of chronic kidney disease." (PMID 40256740, 2025). "CTSS is highly expressed in the kidney tissues of patients with chronic kidney disease (CKD), lupus, diabetic nephropathy and other kidney diseases." (PMID 33912521, 2021). "These evidences indicate that CTSS may be a potential marker in MN progression to end-stage renal disease." (PMID 35812314, 2022). "In addition to the specific macrophage MMP-9 gene modification that accelerated plaque calcification in transgenic rabbits, whole-body elastic CTSS deletion can affect atherogenic diet-induced aortic valvular microcalcification in mice with chronic renal disease." (PMID 37202785, 2023).
multiple sclerosis (10 papers, 2017 to 2025). A progressive autoimmune disorder affecting the central nervous system resulting in demyelination. "In neuroinflammatory disorders, human herpesvirus-6A (HHV-6A) induces CTSS release from neural cells, directly degrading myelin basic protein to initiate demyelination cascades characteristic of multiple sclerosis." (PMID 40692794, 2025). "For example, cathepsin S inhibitors have been investigated for their potential in treating diseases like and multiple sclerosis." (PMID 38521921, 2024). "In patients with multiple sclerosis or asthma who are treated with glucocorticoids, a reduction of the serum ratio of CTSS to Cys C ratio is observed, suggesting that the ratio may reflect the severity of inflammation." (PMID 30038391, 2018). "Therefore, the inhibition of cathepsin S may be particularly effective in treating inflammatory Th1-driven, mDC or B cell-driven autoimmune processes, such as psoriasis or multiple sclerosis, while at the same time preserving tolerogenic pDC function." (PMID 28769925, 2017).
periodontitis (10 papers, 2010 to 2025). An acute or chronic inflammatory process that affects the tissues that surround and support the teeth. "Critically, PU.1-dependent CTSS induction mediates periodontitis progression, underscoring its pathogenic role in inflammatory disease mechanisms." (PMID 40692794, 2025). "Our findings provide original evidence that cathepsin S is increased in periodontal cells and tissues under inflammatory and infectious conditions, suggesting a critical role of this autophagy-associated molecule in the pathogenesis of periodontitis." (PMID 29362520, 2017). "In the context, we suggested that CTSS might play an essential role in bone loss involved in periodontitis progression by interacting with IRF8." (PMID 26334995, 2015). "Therefore, regulation of CTSS might be a critical pathogenic mechanism in periodontitis, which should be investigated in further studies." (PMID 29362520, 2017). "Emerging evidence demonstrates CTSS promotes NF-κB activation in autoimmune encephalomyelitis, hepatitis, periodontitis, and hyperglycemia-induced endothelial inflammation." (PMID 40692794, 2025). "In the periodontitis model, PU.1-mediated CTSS regulation in macrophages correlates with inflammatory pathway activation (e.g., p38 and NF-κB signaling) and elevated levels of inflammatory factors (e.g., IL-6)." (PMID 40692794, 2025). "Like biopsies from the ligature-induced periodontitis, human gingival tissues from sites of periodontitis also exhibited increased CTSS expression levels." (PMID 29362520, 2017). "In vivo, the regulation of CTSS expression in experimental periodontitis was followed in a rat model over 2 weeks." (PMID 29362520, 2017). "Gingival biopsies from periodontitis patients showed a significantly higher cathepsin S expression than those from healthy gingiva." (PMID 29362520, 2017). "Evidence from a bioinformatics screen that compared the gene expression profile between patients with periodontitis and normal controls has identified the likely involvement of CTSS in periodontitis." (PMID 29362520, 2017). "Analysis by RT-PCR revealed that CTSS expression levels were significantly higher at sites of periodontitis, as compared to control sites." (PMID 29362520, 2017). "Cathepsin S is a cysteine protease and regulator of autophagy with possible involvement in periodontitis." (PMID 29362520, 2017). "A significantly elevated cathepsin S expression in gingival biopsies from rats with experimental periodontitis was found in vivo, as compared to that from control." (PMID 29362520, 2017). "Moreover, as visualized by immunohistochemistry, enhanced CTSS protein staining was also detected in biopsies of periodontitis patients." (PMID 29362520, 2017). "Furthermore, CTSS was identified as a possible periodontitis-related target in a bioinformatics-based approach." (PMID 29362520, 2017). "CTSS is closely related to cathepsin K (CTSK), which has been shown to be upregulated in periodontitis." (PMID 29362520, 2017). "In conclusion, this study identified several genes (CTSS, PLEK, IRF-8, PTGS2 and FOSB) that involved in the development and progression of periodontitis." (PMID 26334995, 2015). "Elucidation of the involvement of CTSS in the regulation of inflammatory and microbial threats in PDL cells might be an approach to further clarify the role of autophagy in periodontitis." (PMID 29362520, 2017). "This study identified genes (CTSS, PLEK, IRF-8, PTGS2, and FOSB) that may be involved in the development and progression of periodontitis." (PMID 26334995, 2015).
psoriasis (10 papers, 2014 to 2025). An autoimmune condition characterized by red, well-delineated plaques with silvery scales that are usually on the extensor surfaces and scalp. "Cathepsin K currently represents the most attractive drug target among the cathepsins, although cathepsin S is also a relevant target in diseases associated with elevated immune response, such as bronchial asthma and psoriasis." (PMID 25587532, 2014). "Other cathepsin family members, such as CTSS, CTSK, and CTSD, have been implicated in the pathology of psoriasis." (PMID 30642337, 2019). "The cysteine protease cathepsin S (CatS) is crucially involved in MHCII processing and T cell stimulation, and elevated levels have been found in patients with RA, psoriasis and pSS." (PMID 31319889, 2019). "CTSH was surrounded by CTSS, CTSD and other critical factors involved in complement and adhesion (e.g., C3 and ICAM1) in the psoriasis network, suggesting that it might trigger inflammatory responses by regulating the neighbors in the network." (PMID 30642337, 2019).
asthma (9 papers, 2016 to 2024). "Findings from animal models have also linked CTSS expression with asthma pathogenesis and atopy." (PMID 32398133, 2020). "The inhibitor used here has previously been utilised in vivo in Apoe-/- mice, observing the effect of CTSS in lung granuloma, atherosclerotic lesions and in a murine asthma model." (PMID 27097645, 2016). "Specifically, we sought to examine causal mediation between PBMC key drivers associated with asthma (PRF1 and NKG7 in the NK cell module; CAPZA2, ATP6AP2, CTSS, and RAB3D from the interleukin module) and nasal key drivers associated with asthma (G3BP1 and INADL from the nasal TCA module)." (PMID 37730635, 2023). "Asthma patients treated with methylprednisone had lower levels of serum CTSS protein." (PMID 32398133, 2020). "In addition, prophylactic CTSS inhibitor treatment reduced OVA-induced mucus obstruction in the airways suggesting a possible therapeutic role for prophylactic CTSS inhibitor treatment in patients with asthma." (PMID 32398133, 2020). "A prior study reported that, unlike COPD patients, patients with asthma have significantly reduced plasma cathepsin S levels when compared to healthy control subjects." (PMID 27994288, 2016).
hepatocellular carcinoma (9 papers, 2014 to 2024). A malignant tumor that arises from hepatocytes. "The precise mechanism via which CD47 modulates cathepsin S secretion in hepatocellular carcinoma and potentially other cell types remains to be elucidated." (PMID 39039207, 2024). "Meanwhile, CD47 regulates tumor initiation and stemness of hepatocellular carcinoma stem cells by triggering the secretion of cathepsin S, which stimulates NF-κB and protease-activated receptor-2 (PAR-2) signaling." (PMID 39039207, 2024). "Furthermore, CTSX is upregulated in metastatic gastric cancer, enhanced levels of CTSB and CTSL accompany malignant ovarian tumors, and CTSS directly supports invasion of hepatocellular carcinoma cell lines." (PMID 27802179, 2016).
liver fibrosis (9 papers, 2018 to 2025). "Our results showed significant upregulation of multiple lysosomal proteins in Lal−/− livers, including CTSS and CTSD, which are known to be important mediators in liver fibrosis and liver cancer progression, along with CD68, a well-established macrophage marker." (PMID 37595802, 2023). "Our recent study has identified cathepsin S upregulation as a central node of ECM remodeling in human fibrotic livers by proteomic screening and demonstrated cathepsin S as a potential target for the diagnosis and treatment of liver fibrosis by exploring its mechanism." (PMID 40368138, 2025). "In particular, we have recently revealed the participation of cysteine cathepsins [Cathepsin B (CTSB) and Cathepsin S (CTSS)] in controlling hepatic NF-κB-dependent inflammation via sirtuin-1 regulation, and the role of CTSB in promoting hepatic stellate cell (HSC) activation and liver fibrosis." (PMID 29541077, 2018).
prostate carcinoma (9 papers, 2015 to 2024). A carcinoma that arises from epithelial cells of the prostate gland. "CTSS and class II MHC genes were once again the most important features, though HLA-B and HLA-C appeared more influential in prostate cancer risk." (PMID 37173324, 2023). "In addition, we also propose that SPINT2 (OR: 1.05, 95% CI 1.03–1.06), GSTP1 (OR: 0.82, 95% CI 0.74–0.90), and CTSS (OR: 0.91, 95% CI 0.88–0.95) may serve as potential therapeutic targets in prostate cancer." (PMID 37735436, 2023). "The other most prominent proteases in prostate cancer include MMPs, ADAMs, ADAMs with thrombospondin-1 motifs (ADAMTS), and CTSs." (PMID 38255186, 2023).
type 2 diabetes (9 papers, 2013 to 2025). "Higher CTSS levels are linked to inflammatory cytokine release, which leads to the onset of type 2 diabetes." (PMID 36982499, 2023). "In this study, we investigated the relationship between circulating cathepsin S and cardiovascular disease in patients with type 2 diabetes." (PMID 33746900, 2021). "Meanwhile, this study provides a novel insight into the potential role of cathepsin S in the diagnosis of CVD in patients with type 2 diabetes." (PMID 33746900, 2021). "Taken together, the present study found that circulating cathepsin S was significantly higher in the CVD (+) group than that in the CVD (−) one among type 2 diabetes patients." (PMID 33746900, 2021). "Circulating cathepsin S was significantly higher in the CVD (+) group than that in the CVD (−) one among type 2 diabetes." (PMID 33746900, 2021). "Collectively, our study indicated that serum cathepsin S levels were strongly and independently associated with CVD in patients with type 2 diabetes." (PMID 33746900, 2021). "Hence, we undertook this study and investigated the cross-sectional community-based association between circulating cathepsin S and CVD in patients with type 2 diabetes." (PMID 33746900, 2021). "Although we cannot establish causality in this study, there are several potential mechanisms that may explain the association between circulating cathepsin S and CVD in type 2 diabetes patients." (PMID 33746900, 2021). "The present study aims to elucidate the relationship between circulating cathepsin S and cardiovascular disease (CVD) in patients with type 2 diabetes." (PMID 33746900, 2021). "However, little is known about the direct relationship between circulating cathepsin S and CVD in the context of type 2 diabetes." (PMID 33746900, 2021). "In addition, the optimal cutoff value of cathepsin S in detecting CVD in patients with type 2 diabetes has not been suggested to date." (PMID 33746900, 2021). "Thus, the relationship between cathepsin S and CVD in patients with type 2 diabetes has not been unveiled so far." (PMID 33746900, 2021).
coronary artery disease (8 papers, 2013 to 2022). "The RNA editing enzyme ADAR1 levels and the extent of CTSS RNA editing are associated with changes in CTSS levels in patients with coronary artery diseases." (PMID 29867565, 2018). "ADAR1 levels and the extent of CTSS RNA editing are associated with changes in cathepsin S levels in patients with atherosclerotic vascular diseases, including subclinical atherosclerosis, coronary artery disease, aortic aneurysms, and advanced carotid atherosclerotic disease." (PMID 34969816, 2022). "In a clinical study performed on 120 patients with high serum cathepsin S levels vs. age and sex-matched controls, the incidence of coronary artery disease and hypertension was significantly higher, and the intima-media thickness was also increased." (PMID 35453881, 2022).
lung fibrosis (8 papers, 2018 to 2025). "Cathepsin S (CTSS) levels were significantly decreased in the serum of SSc patients compared with healthy controls, and the reduced levels were reflective of the severity of SSc lung fibrosis." (PMID 36769282, 2023). "On the other end, in its soluble form, decorin is an endogenous ligand to TLR2 and TLR4 and can activate the p38 MAPK and ERK pathways, leading to pro-inflammatory signaling; it may also promote lung fibrosis when degraded by cathepsin-S because fragmentation disrupts its anti-fibrotic capabilities." (PMID 36835058, 2023).
ovarian carcinoma (8 papers, 2010 to 2025). A malignant neoplasm originating from the surface ovarian epithelium. "These important roles of CTSs in cancer development encouraged us to examine the expression of CTSs in the chicken ovarian cancer model." (PMID 20727192, 2010). "The results of the present study demonstrate that CTSB, CTSC, and CTSS are upregulated in cancerous ovaries of chickens, suggesting that CTSB, CTSC, and CTSS have potentially important functions in the development of ovarian cancer in chickens." (PMID 20727192, 2010). "Our results suggest that CTSB, CTSC, and CTSS have important functions in the development of epithelial ovarian cancer." (PMID 20727192, 2010). "Hence, SPRi signals quantify the concentrations of the cathepsin S biomarker, considering the high concentrations detected in ovarian cancer patients." (PMID 40277517, 2025). "Nevertheless, no studies have investigated the expression of CTSs in chickens with ovarian cancer." (PMID 20727192, 2010). "However, no studies have investigated the expression of CTSs in chickens with ovarian cancer." (PMID 20727192, 2010).